CXCL12 (C-X-C motif chemokine ligand 12)
Diseases named in the same sentence as CXCL12 in open-access papers (continued):
Sharing a sentence is not in itself a finding about the gene and the disease.
breast carcinoma (continued). "In addition, CIP significantly downregulated the CXCL12 induced motility of breast cancer cells and molecular docking calculations revealed that all compounds bind to Akt2 kinase with high docking scores compared to the library of previously reported Akt2 inhibitors." (PMID 27097161, 2016). "In addition, we used a xenograft mouse model established by intracardiac injection of tumor cells to show that ANGPTL2 knockdown in breast cancer cells attenuates tumor cell responsiveness to CXCL12 by decreasing CXCR4 expression in those cells, thereby decreasing bone metastasis." (PMID 25773070, 2015). "Together, our mechanistic in vitro assays and in vivo results suggest that a reduction in chemokine CXCL12 expression, with an enhancement of CXCR4 expression, provoked by COUP-TFI, could be associated with an increase in the invasive potential of breast cancer cells." (PMID 24906407, 2014). "In addition, paracrine signal loops between TAMS and tumor-aiding fibroblasts that secrete CXCL12 to CXCR4 over-expressing breast cancer cells increase the effectiveness of epidermal growth factor (EGF) gradients significantly increasing the occurrence of metastasis." (PMID 25385001, 2014). "Furthermore, the CXCR4/CXCL12 axis could mediate the chemotaxis of cancer stem cells that are involved in the metastasis of breast cancer stem cells and cancer cell survival and proliferation." (PMID 24475985, 2014). "However, the exact mechanisms of how CXCR4 and CXCL12 enhance metastasis and/or tumor growth and their full implications on breast cancer progression are unknown." (PMID 24810923, 2014). "Therefore, amoeboid transitions in migrating breast cancer cells induced via exposure to CXCL12 may play a role in one or multiple steps in metastasis." (PMID 23024796, 2012). "Taken together, CXCR4 and CXCL12 may indeed play critical roles in breast cancer metastasis." (PMID 22485156, 2012). "In this study, we investigated the role of CXCR4/CXCL12 in breast cancer cell migration and adhesion with a focus on its dependence on liver ECM components that may provide an organ-specific microenvironment for rapid tumour cell extravasation into this major metastatic organ." (PMID 22253872, 2012). "Although CXCL12 signaling has been implicated in breast cancer metastasis as a homing mechanism for cancer cells to common sites of metastasis, not much is currently known about the role of CXCL12 signaling in the early steps of metastasis within the primary tumor." (PMID 22152016, 2011). "Several studies have shown how acquisition of the chemokine receptor CXCR4 by breast cancer cells can promote specific, chemotactic recruitment to remote sites such as the bone marrow, lymph nodes, liver and lung in response to localised expression of the specific chemokine ligand, CXCL12." (PMID 24212798, 2011). "Importantly, CXCL12 has been found to be expressed in many human solid tumors including breast, pancreas and prostate cancers, and glioblastoma, with high levels of CXCL12 expression correlating with poor prognosis of breast cancer patients." (PMID 22152016, 2011). "Thus therapies that incorporate boosting of CXCL12 levels at the primary tumor site may be a more holistic treatment of metastatic breast cancers by enhancing the anti-tumor immune response." (PMID 20849618, 2010). "The current study was designed to determine the minimal chain length of a heparin oligosaccharide that could significantly inhibit CXCL12-mediated breast cancer metastasis, while abrogating the potential anticoagulation problems associated with the use of heparin as an antimetastatic treatment." (PMID 17726466, 2007). "Blockade of CXCL12/CXCR4 signaling inhibits intrahepatic cholangiocarcinoma and breast cancer progression and metastasis via inactivation of canonical Wnt pathway." (PMID 40211853, 2026).
breast carcinoma (continued). "For example, in breast cancer, TGF‐β activates the TGF‐β/Smad signaling pathway, promoting myofibroblastic CAFs (myCAFs) formation and stimulating CXCL12 secretion, which creates a positive feedback loop through CXCR4 activation." (PMID 41164803, 2025). "Recent studies have identified iCAF in several tumour types, including pancreatic cancer and breast cancer, using a variety of markers that encompass inflammatory cytokines and other genes (CXCL1, CXCL8, CXCL12, IL6, CFD, DPT)." (PMID 39757146, 2025). "Osteopontin, secreted by breast cancer cells, reprograms fibroblasts into a proinflammatory state, inducing Epithelial Mesenchimal Transition (EMT) in cancer cells via CXCL12 secretion." (PMID 40230452, 2025). "In human breast cancer, CAFs recruited monocytes via MCP1, CXCL12, CCL2, and CCL16, leading to their differentiation into M2-like macrophages that exert immunosuppressive effects through the PD-1 axis." (PMID 40230452, 2025). "The CXC chemokine receptor 4, or CXCL12/CXCR4 axis, has been shown to contribute to the growth of primary breast carcinogenesis and is essential for the metastasis of breast cancer cells, which in turn leads to the establishment of secondary tumors." (PMID 41348904, 2025). "CXCR4 expression promotes breast cancer metastasis to organs where there is an abundance of its ligand, SDF-1/CXCL12, such as the lymph nodes, brain, skeleton/bone marrow, liver and lungs." (PMID 40075611, 2025). "For instance, CXCL12 and SLC (CCL-21) bind to CXCR4 and CCR7 receptors on breast cancer cells, respectively, promoting tumor cell migration to the lymphatic system along a chemotactic gradient." (PMID 40084140, 2025). "For example, the CXCR4 receptor, primarily activated by CXCL12, can be used to direct nanoparticles specifically to cancers expressing CXCR4, such as ESCA, breast cancer and ovarian cancer." (PMID 40134607, 2025). "When breast cancer cells express their cognate receptor, CXCR4, CXCL12 functions as a chemoattractant at secondary tumor locations, causing the cancer cells to migrate and homing." (PMID 41348904, 2025). "In 2013, gene expression analysis identified 809 genes upregulated in CAFs, including CCL18, CXCL12, MMP9, and PLK1, which are involved in cell cycle regulation, adhesion, and secretion, further supporting breast cancer progression." (PMID 40230452, 2025). "For instance, our research revealed that CAFs derived from breast carcinomas promote tumor growth and angiogenesis by secreting elevated levels of the C‐X‐C motif chemokine ligand 12 (CXCL12/SDF‐1)." (PMID 39887653, 2025). "First, TNC binds to CXCL12, which retains CD8+ T cells in the stroma and limits cytotoxicity, thereby promoting breast cancer progression." (PMID 41174721, 2025). "Pathways identified in CXCL12 and FB2 fibroblast cell clusters from RA and in the B2 cell cluster from HER2+ breast cancer patients support that TMEM230/RNASET2/SDC2/IRF1 axis have pleiotropic functions." (PMID 40862725, 2025). "Further studies have found that these four CAF subpopulations are also present in axillary metastatic lymph nodes of breast cancer, where CAF-S1 and CAF-S4 drive cancer metastasis through the CXCL12/TGFβ and NOTCH signaling pathways, respectively." (PMID 40890855, 2025). "In breast cancer, CAF-S1 recruits CD4+CD25+ T lymphocytes via CXCL12 secretion, followed by direct contact with T cells through surface molecules OX40L, PD-L2, and JAM2 to prolong their retention." (PMID 40890855, 2025). "Osteoblasts and stromal cells in the bone marrow secrete CXCL12, creating a chemotactic gradient that attracts CXCR4-expressing tumor cells, facilitating prostate and breast cancer cell homing to the bone." (PMID 40606222, 2025). "Extensive research links CAFs to breast cancer progression, with studies showing that CAFs secrete SDF-1/CXCL12 and HGF, both of which promote breast cancer growth and metastasis." (PMID 38533507, 2024).
breast carcinoma (continued). "Activation of HIF-1α signaling increases CXCL12 blood levels, which directly activates the CXCR4 receptor and promotes the migration of breast cancer cells to bone." (PMID 38464516, 2024). "Future studies will be needed to determine the best practice and compounds for the simultaneous inhibition of the CXCL12/CXCR4 axis and the MDM2/MDMX axis to block breast cancer metastasis." (PMID 39766093, 2024). "CXCL12 interacts with CXCR4, a receptor expressed on breast cancer cells, to guide their migration toward high-CXCL12 areas." (PMID 39605887, 2024). "Research findings indicate that the CXCL12 and STAT3 proteins are significantly upregulated in various malignancies, including breast cancer, lung cancer, hepatocellular carcinoma, esophageal cancer, bladder cancer, and leukemia." (PMID 38920657, 2024). "Further investigations reveal that the CXCL12/CXCR4 axis phosphorylates JAK2, thereby activating the STAT3 signaling pathway to promote breast cancer proliferation and metastasis." (PMID 38920657, 2024). "In breast cancer, the recruitment of monocytes to the tumor is triggered by the CAF-driven CXCL12/CXCR4 axis, which also supports the acquisition of an immunosuppressive lipid-associated macrophage (LAM) phenotype." (PMID 38715072, 2024). "The chemokine CXCL12, also known as stromal cell-derived factor-1 (SDF-1), binds with high affinity to the CXCR4 receptor and functions to drive breast cancer progression." (PMID 39766093, 2024). "Among others, prostate and breast cancers preferentially metastasize to the bone and lungs via the CXCR4/CXCL12 axis, and approaches aimed at inhibiting this interaction have proven to significantly reduce metastatic spread." (PMID 38803493, 2024). "ORL inhibits angiogenesis (VEGF, MMP-9, and CXCR4/CXCL12) and fatty acid synthesis (ACLY, ACC, and FASN) genes and protein expression with the induction of apoptotic genes in different breast cancer cell lines." (PMID 38256929, 2024). "Again, in breast cancer, ACKRs that scavenge CXCL12 limited tumor growth and metastasis in CXCR4+ breast cancer cells possibly due to reduced neovascularization or disruption of CXCL12-guided egress through tumor-associated lymphatic vessels." (PMID 38786066, 2024). "In breast cancer, WWP1 negatively regulates CXCL12-induced CXCR4 lysosomal degradation, thereby facilitating breast cancer cell migration and bone metastasis, leading to poor prognosis (Fig. 5C1,)." (PMID 38129384, 2023). "For example, in a mouse model of breast cancer with lung metastasis, the chemokine receptor, CXCR4, and its ligand, CXCL12, control the metastasis of the breast cancer cells, where the expression of CXCL12 is high in breast cancer cells." (PMID 37251542, 2023). "Overexpression of SDF-1/CXCL12 by αSMA+ CAFs and simultaneous downregulation of mDia2 protein triggered pro-angiogenic secretome profile in breast cancer." (PMID 36793444, 2023). "SDF-1, currently known as CXCL12, directly binds to its receptor CXCR4, a G-protein-coupled receptor, to induce tumor angiogenesis, thereby promoting breast cancer growth." (PMID 37496657, 2023). "For instance, CXCL12, CCL2, CCL5, and CXCL1 have been shown to regulate growth and stimulate the proliferation of melanoma, glioma, prostate cancer cells, and breast cancer cells." (PMID 37762405, 2023). "As curcumin exhibited an inhibitory effect on the CXCL12/CXCR4 axis and the NF-κB signaling pathway in MCF7 cells, it was demonstrated that curcumin has the potential to modulate breast cancer TME by repressing both ADMSCs and cancer cells." (PMID 38004606, 2023). "According to this study based on the expression of C-X-C motif chemokine ligand 12 (CXCL12) and CXCR7 mRNA, chemotherapy/MF/PTT combined therapy exhibited the greatest reduction in breast cancer metastatic activity." (PMID 36986729, 2023).
breast carcinoma (continued). "DPP-4 knockdown significantly promoted the levels of CXCL12, CXCR4, phospho-mTOR, and HIF-1α in breast cancer cell lines." (PMID 37760498, 2023). "It was suggested that curcumin disrupts the positive feedback loop mediated by CXCL12/CXCR4/NF-κB/SHH between CAFs and MCF7 cells, exhibiting its therapeutic potential by regulating the breast cancer TME." (PMID 38004606, 2023). "In cell clusters associated with MSCs or the progeny (i.e., cancer-associated fibroblasts, CAFs) in the whole tumor data, it was evident that MSC-related cells were the major source of THY1 (CD90), CXCL12 and ACTA2 expression in breast cancer patient samples." (PMID 36940196, 2023). "As expected, we also found that the aggressive breast cancer cell lines MDA-MB-231 and 4T1 exhibited higher CXCL12/CXCR4 levels than did MCF 10A normal epithelial breast cells." (PMID 37760498, 2023). "Regarding vascularisation, CXCL12 and CCL2 are the most potent angiogenic chemokine, which enables the adequate oxygen supply required in metastatic breast cancer." (PMID 37680708, 2023). "It is described that the released CXCL12 and IGF1 produced by MSCs activate the PI3K/AKT signaling pathway in breast cancer cells and then shift the cancer cell population towards more bone metastatic ones." (PMID 38022534, 2023). "Cochrane’s Q test did not provide evidence of heterogeneity between CCL1 (p = 0.227), CCL2 (p = 0.982), CCL18 (p = 0.221), CXCL5 (p = 0.533), CXCL12 (p = 0.977), and CXCL13 (p = 0.520) and breast cancer." (PMID 38075694, 2023). "The CXCL12/CXCR4 signaling pathway plays an important role in the growth and angiogenesis of primary breast cancer." (PMID 37760498, 2023). "DPP-4 suppression augmented CXCL12/CXCR4 levels, which led to autophagy and HIF-1α in breast cancer cells; a CXCR4 inhibitor reversed these DPP-4 inhibition-induced alterations." (PMID 37760498, 2023). "The nuclear factor kappa B (NF-κB) signaling pathway is downstream of CXCL12/CXCR4, modulating breast cancer progression along with inflammation, cell proliferation, migration, and invasion." (PMID 38004606, 2023). "CXCR4 is downregulated in dormant breast cancer cells in the lungs, and the upregulation of CXCR4 with its ligand, CXCL12, promotes AKT signaling and proliferation." (PMID 37440925, 2023). "In pancreatic and breast cancer, the polarization and recruitment of M2 macrophages is regulated by the POU1F1/CXCL12/CXCR4 signaling axis to promote tumor metastasis." (PMID 37415241, 2023). "It is well described that in BC, distinct amounts of S1 CAFs and S4 CAFs were found in metastatic breast cancer axillary lymph nodes, conducting tumor cell migration and invasion via CXCL12, TGFβ, and NOTCH signaling pathways, respectively." (PMID 37784082, 2023). "Together, CXCL12 and TGF-β form autocrine signaling loops in myofibroblasts of invasive human breast cancers." (PMID 36268282, 2022). "CXCL12 can stimulate and induce the expression of CXCR7 as well as CXCR4 and various EMT markers in human breast cancer cells." (PMID 36077241, 2022). "In a rodent model of breast cancer, TAFs were observed to promote monocyte migration into the TME by secreting pro-inflammatory cytokines such as MCP-1 and CXCL12/SDF-1." (PMID 35814453, 2022). "Chemokine receptors CXCR4 and CCR7 ligands (CXCL12 is also referred to as stromal cell-derived factor-1 [SDF-1] and CCL21) are widely expressed on human breast cancer cells and on the organs that tumors normally metastasize." (PMID 36679904, 2022). "This study provides a strategy to inhibit the initiation and progression of breast cancer in patients with elevated S100A9 and/or CXCL12 expression." (PMID 35304461, 2022). "Probably due to decreased CXCL12 cleavage, DPP-IV ablation promoted epithelial–mesenchymal transition, breast cancer metastasis, and the upregulation of ABC transporters via the CXCL12/CXCR4/mTOR axis." (PMID 35565202, 2022).
breast carcinoma (continued). "LMWH inhibited the interaction between CXCL12 and CXCR4, thereby reducing the metastatic spread of breast cancer cells in mice." (PMID 36296562, 2022). "Insulin‐like growth factor I and the chemokine CXCL12 and its receptor, CXCR4, are important for directional migration of breast cancer cells." (PMID 35520391, 2022). "As a direct effect on breast cancer, these cells were reported to trigger EMT by activating the CXCL12 and TGFβ pathways in breast cancer cells." (PMID 36010901, 2022). "Numerous investigations have shown that extracellular CXCL12 is overexpressed in different types of tumors and promotes the occurrence, invasion, and metastasis of tumors such as GC, CRC, breast cancer, and melanoma." (PMID 35647303, 2022). "Among these, the interaction between chemokine CXCL12 and its receptor CXCR4 is the basis of the metastasis of breast cancer." (PMID 36296562, 2022). "FAM189A2‐knockout prohibits CXCL12‐induced endocytosis of CXCR4, thereby enhancing the effects of CXCL12 on the chemotaxis and mammosphere formation of breast cancer cells." (PMID 34927784, 2022). "However, in other studies, CXCL12 G801A polymorphism was not a risk factor for breast cancer." (PMID 35079936, 2022). "To investigate the CXCL12-mediated regulation of the interaction between β-arrestin 2 and PKM2 in vivo, we used an orthotopic tumor xenograft model of human breast cancer." (PMID 35681470, 2022). "AhR–dependent mechanisms for the inhibition of breast cancer by AhR agonists are variable and include the downregulation of multiple genes/gene products such as CXCR4, MMPs, CXCL12, SOX4 and the modulation of microRNA levels." (PMID 36428667, 2022). "The interaction between CXCR4 and its specific ligand, i.e., stromal-derived factor-1 (SDF1 or CXCL12), is of considerable importance in the development of invasion and metastasis of different solid tumors, particularly breast cancer." (PMID 35236304, 2022). "The CXCL12/CXCR4 axis mediates EMT via activation of PI3K-Akt/PKB in human sacral chondrosarcoma, breast cancer, and oral carcinoma cells." (PMID 36268282, 2022). "Inhibition of dipeptidyl peptidase (DPP)-4 stimulated CXCL12/CXCR4 expression and activated mTOR signaling, which further induced epithelial-mesenchymal transition of breast cancer cells and metastasis." (PMID 34234860, 2021). "Metastatic breast cancer cells express high levels of CXCR4; its ligand CXCL12 is highly secreted by stromal cells within these tissues." (PMID 34427969, 2021). "Several differentially expressed mRNAs in HER2-positive breast cancer (including CXCL2, CXCL12, CXCL10, CXCL11, CXCL9 and CXCL14) were enriched in the biology processes of chemokine receptor binding and chemokine activity." (PMID 34257572, 2021). "Previous studies have demonstrated that POU1F1/CXCL12/CXCR4 axis contributes to macrophage recruitment and polarization, thereby promoting breast cancer metastasis." (PMID 33927188, 2021). "TN1, a peptide that simulates the CXCL12 recognition site for CXCR4 and acts as a competitive antagonist, was modified to reduce its toxicity and increase its stability and is now used for breast cancer treatment." (PMID 33530455, 2021). "Variations in CXCL12 expression levels are regulated in part by MSCs, and, accordingly, when CXCL12, CXCR4, or ER were blocked in a human breast carcinoma cell model, MSC-induced proliferation and migration were significantly decreased." (PMID 33530455, 2021). "Study of breast cancer suggested that FOXP3 function as a key tumor suppressor through the up-regulation of CXCR4 and down-regulation of CXCL12, which thereby stimulate cell migration." (PMID 33869044, 2021). "The CXCL12/CXCR4 axis plays a pivotal role in homing and invasion of bone-metastatic breast cancer cells." (PMID 34064589, 2021). "Targeting a single paracrine signaling pathway, e.g., CCL21/CCR7 or CXCL12/CXCR4, has been shown to reduce lymphatic metastasis in murine models of breast cancer." (PMID 34885152, 2021).